GATA3 (GATA binding protein 3)
Diseases named in the same sentence as GATA3 in open-access papers (continued):
Sharing a sentence is not in itself a finding about the gene and the disease.
leukemia (16 papers, 2013 to 2026). A malignant (clonal) hematologic disorder, involving hematopoietic stem cells and characterized by the presence of primitive or atypical myeloid or lymphoid cells in the bone marrow and the blood. "Emerging evidence has discussed the implication of genetic variants of GATA3 in the development and progression of leukemia." (PMID 39768217, 2024). "Providing further conceptual links between pioneer factor function and 3D genome structure, a recent report demonstrated that GATA3 gene expression levels can alter chromatin architecture in leukemia, and that polymorphisms in GATA3’s intronic regulatory sequences could impact its expression." (PMID 35902807, 2022). "The mechanism by which GATA3 promotes thymocyte transformation and leukemia survival is not well understood." (PMID 35514954, 2022). "In established E2a-/- leukemia lines re-expression of E2A proteins alters the transcription of numerous genes including Gata3, which is indirectly regulated by E2A-mediated induction of GFI1B." (PMID 35514954, 2022). "We examined the RNA expression of three hematopoietic GATA transcription factors (GATA1, GATA2, and GATA3) in a total of 1,644 pediatric leukemia patients with AML (n = 297), T-ALL (n = 99), and B-ALL (n = 1,248) using RNA-seq data available at St." (PMID 35087776, 2021). "Consistently, STAT4 expression decreases in leukemia cells treated with shRNA against GATA3, which was also confirmed in previous reports." (PMID 28415601, 2017). "Our results are in good agreement with the prior knowledge regarding Gata3’s activity: the top two tissues predicted for Gata3 are E14.5 liver cells and the adult leukemia cell line." (PMID 24238150, 2013). "Gata3 is known to function in mouse fetal liver haematopoiesis, and its expression had also been observed in leukemia cells." (PMID 24238150, 2013). "Aberrant GATA3 expression in different types of leukemia reveals its special role in oncogenesis." (PMID 36714653, 2022). "Interestingly, CBLB, which is the potential downstream target of GATA3 in leukemia as well as LCLs according to our results, contains one SNP (i.e., rs4894953) in its enhancer region." (PMID 28415601, 2017). "Moderate enrichment of DNA-binding motifs for embryonic transcription factors (for example, Sox10 and Eomes) and T-cell transcription factors (for example, Tbet and GATA3) were found, consistent with adoption of a more primitive transcription program in MLLr leukemia." (PMID 27462455, 2016). "Ectopic expression of GATA3 under the control of the CD2 promoter is able to promote T cell transformation suggesting that this failure to repress Gata3 could be a key event in the generation of E2a-/- leukemias." (PMID 35514954, 2022). "Statistically significant differences between the leukemia and MRD-negative groups were achieved by JUP, NT5C3B, MYC, GATA3, PTK7, CNP, SNAI1, and ICOSLG." (PMID 41596324, 2026). "Given the critical role that GATA3 plays in early lymphoid development, we investigated GATA3 in ETP-ALL, a stem cell-like leukemia blocked at the crossroads of lymphoid and myeloid differentiation." (PMID 27658391, 2016). "Finally, we found 137 genes that are potential involved in GATA3-related regulatory network with nine independent pediatric ALL patient cohorts, and got validated in another leukemia cohort containing all ages of B-ALL patients." (PMID 28415601, 2017). "However, a test of GATA3 mRNA expression in different types of leukemia demonstrated that compared to ETP-ALL patients, some B-ALL and non-ETP ALL patients showed extremely high GATA3 expression, suggesting that GATA3 may also act as an oncogene." (PMID 36714653, 2022). "High expression of JUP, NT5C3B, MYC, GATA3, PTK7, CNP, and ICOSLG clearly differentiated the leukemia from the non-leukemia group." (PMID 41596324, 2026). "Importantly, JUP, NT5C3B, MYC, and GATA3, PTK7, CNP, and ICOSLG differentiated both non-pathological conditions (non-leukemia and MRD-negative) from leukemia samples." (PMID 41596324, 2026).
psoriasis (16 papers, 2011 to 2025). An autoimmune condition characterized by red, well-delineated plaques with silvery scales that are usually on the extensor surfaces and scalp. "Unlike GATA3, the expression of miR-155 significantly increased in the tissues of psoriasis lesions and is negatively associated with IL-37 and GATA3." (PMID 34025671, 2021). "To identify other transcription factors associated with downmodulated GATA3expression in psoriatic epidermis, we compared the gene expression profiles fromepidermis-specific GATA3-deficient mice with that of lesionalepidermis of patients with psoriasis." (PMID 21611195, 2011). "Likely, the IL-4/STAT6 and IL-4/GATA3 signaling pathways prevent hyperactive Th1 responses in psoriasis." (PMID 37270497, 2023). "Among the associated genes were EGR3, GATA6, GATA3, and FOXN3, which play important roles in psoriasis." (PMID 34068434, 2021). "We also examined the sublineages of iNKT cells and found that the MFI of GATA3+iNKT cells and RORγt+iNKT cells were significantly increased in psoriasis patients." (PMID 35186952, 2021). "FOXN3, regulating cell differentiation and cell cycle, is down-regulated along with GATA3 in psoriasis." (PMID 34068434, 2021). "In psoriasis, miR155 was also reported to regulate GATA3 downstream IL-37 mediated inflammatory responses." (PMID 34777377, 2021). "Although GATA3 in keratinocytes contributes to cell differentiation and the expression of barrier proteins, GATA3 expression is reduced in both inflammatory skin diseases of AD and psoriasis." (PMID 32235696, 2020). "Samples from lesional and non-lesional skin from patients suffering from atopic dermatitis or psoriasis as well as samples from healthy controls were analysed by immunohistochemistry staining for their expression patterns of GATA3 in the epidermis." (PMID 28928464, 2017). "No tendency for divergent gene expression of FLG, FLG2, IVL, LOR or HRNR in GATA3 silenced cells when compared to control cells was visible under psoriasis-like conditions." (PMID 28928464, 2017). "In contrast, 3D skin equivalents made of GATA3 silenced keratinocytes which were cultivated under psoriasis like conditions showed increased FLG2 protein levels when compared to the correlated controls (controls shRNA) by trend." (PMID 28928464, 2017). "We observed less GATA3 protein in 3D skin equivalents made with GATA3 silenced keratinocytes than in the skin models comprised of control cells under ns and psoriasis like conditions by trend." (PMID 28928464, 2017). "Standard NB-UVB therapy increased the expression of GATA3 mRNA in psoriatic skin towards the levels found in healthy controls and the restoration of GATA3 expression correlated with psoriasis improvement." (PMID 23594996, 2013). "GATA3 has been shown to be downregulated in patients with psoriasis, a chronic inflammatory skin disease characterized by a high keratinocyte proliferation rate." (PMID 23594996, 2013). "Our finding that epidermal GATA3 expression isdownmodulated in both psoriasis and epidermal regeneration is consistent withpreviously described parallels between these conditions." (PMID 21611195, 2011). "Our results show that the epidermal expression of the transcription factor GATA3 isconsistently decreased in psoriasis, in psoriasiform dermatitis in mice, and duringepidermal wound healing." (PMID 21611195, 2011). "We therefore stimulated skin biopsies from healthy volunteers ex vivowith different cytokines important in the pathogenesis of psoriasis and measuredepidermal GATA3 mRNA." (PMID 21611195, 2011). "Since GATA3 serves as a key switch inboth epidermal and T helper cell differentiation, we investigated its functionin psoriasis." (PMID 21611195, 2011). "Inconclusion, GATA3 expression is downmodulated in the regenerating epidermisafter wounding and tape stripping, and in psoriasis." (PMID 21611195, 2011).
psoriasis (continued). "We also show that in healthy human skin explants the Th2 cytokineIL-4 was the only cytokine, out of a broad array of cytokines critical in psoriasis,able to significantly and effectively induce GATA3 expression in the epidermis." (PMID 21611195, 2011). "Therefore, when GATA3 gene was deleted, a complete suppression of Th2 cell differentiation led to exacerbation of psoriasis due to a predominantly Th1 response." (PMID 37270497, 2023). "Both GATA3 and STAT6 may act in concert with the Notch signaling pathway to control an optimal Th2 cell response during psoriasis, in which GATA3 is the central regulator for maintaining the effectiveness of Th2 response." (PMID 37270497, 2023). "Multiple comparison post test revealed that the epidermis of lesional AD and psoriasis samples have a significant reduction in GATA3 expression in these cell layers when compared to healthy skin (AD vs. healthy p = 0,0107; psoriasis vs. healthy p = 0,00259 (both Holm-Sidak method))." (PMID 28928464, 2017). "When analysing skin samples from atopic dermatitis and psoriasis patients or healthy controls, we detected decreased expression of GATA3 in the stratum spinosum and stratum granulosum of atopic dermatitis and psoriasis patients when compared to healthy controls." (PMID 28928464, 2017). "In conclusion, this study shows that the epidermal expression of the transcriptionfactor GATA3 is consistently downregulated under conditions of keratinocytehyperproliferation and altered differentiation such as in psoriasis, in murinepsoriasiform dermatitis and in wound healing." (PMID 21611195, 2011). "Here we show that in keratinocytes GATA3 is strongly induced by IL-4.Psoriasis is currently viewed as a predominantly Th1/Th17 disease, where the Th1cytokines (IFN-γ) and Th17 cytokines (IL-17, IL-22) together with IL-23 suppressthe production of IL-4 in T lymphocytes." (PMID 21611195, 2011). "List1 of genesdifferentially expressed in both psoriasis and GATA3 −/−mice." (PMID 21611195, 2011). "Furthermore, we compared gene expression changes inpsoriasis and in epidermis-specific GATA3-knock-out mice, and searched for factorsthat can correct the downregulated GATA3 expression in psoriasis." (PMID 21611195, 2011). "Polymorphisms in the GATA3 gene or geneticlinkage have not been reported for psoriasis, but have been found for atopicdermatitis." (PMID 21611195, 2011). "Furthermore, IL‐4 upregulates the expression of the transcription factor GATA3 in epidermal cells and keratinocytes, promoting Th2 immune responses while counteracting the proinflammatory Th1 and Th17 responses commonly observed in psoriasis." (PMID 41211170, 2025). "However, miR-155/GATA3/IL-37 may be an available option for psoriasis treatment, which requires additional clinical studies." (PMID 34025671, 2021). "As psoriasis is characterized by altered keratinocyte proliferation anddifferentiation and by infiltration of activated Th1 and Th17 cells, processes thatare linked to altered GATA3 expression, we hypothesized that epithelial GATA3 mightplay an important role in the pathogenesis of psoriasis." (PMID 21611195, 2011). "While the Mean Fluorescence Intensity (MFI) of T-bet+iNKT cells (iNKT1) remained unaltered, the MFI of GATA3+iNKT cells (iNKT2) and ROR-γt+iNKT cells (iNKT17) were significantly increased in psoriasis patients." (PMID 35186952, 2021). "Briefly, the miR-155/GATA3/IL-37 axis regulates the production of CXCL8 and IL-6 by stimulating TNF-α to affect the progression of psoriasis." (PMID 34025671, 2021). "We further analyzed the ratio of GATA3+iNKT cells vs ROR-γt+iNKT cells and found a decrease in psoriasis patients." (PMID 35186952, 2021). "Still, single-cell analysis of skin tissues and peripheral blood mononuclear cells from Palmoplantar pustulosis, a specific psoriasis subtype, revealed heightened expression and co-expression of TH17 (KLRB1/CD161) and TH2 (GATA3) in a subset of memory CD4+ T cells." (PMID 38596682, 2024).
psoriasis (continued). "Moreover, we found that the ratio of GATA3+iNKT cells vs ROR-γt+iNKT cells decreased and the ratio of ROR-γt+iNKT cells vs T-bet+iNKT cells increased in psoriasis patients, suggesting that there may be imbalance of iNKT cells sublineages in psoriasis." (PMID 35186952, 2021). "3D skin equivalents made of GATA3 shRNA transduced cells showed the tendency to express less FLG when compared to the respective control 3D skin equivalent under all investigated conditions (ns, AD-like (IL-4 and IL-13), and psoriasis-like (IL-22, OSM, IL-17, and TNFα) conditions)." (PMID 28928464, 2017). "GATA3 expressionwas also determined in situ at the protein level, in skinbiopsies from healthy individuals, as well as in lesional and non-lesional skinbiopsies of patients with psoriasis." (PMID 21611195, 2011). "GATA3 expression was also markedly decreased ininflamed skin of mice with a psoriasiform dermatitis induced with imiquimod.Tape-stripping of non-lesional skin of patients with psoriasis, a standardizedpsoriasis-triggering and skin regeneration-inducing technique, reduced theexpression of GATA3." (PMID 21611195, 2011).
endometrial carcinoma (15 papers, 2009 to 2025). A malignant tumor arising from the epithelium that lines the cavity of the uterine body. "In conclusion, GATA3 expression is associated with an aggressive phenotype of endometrial carcinoma and provides independent prognostic information." (PMID 39118796, 2024). "GATA3 expression is associated with an aggressive phenotype and poor patient survival in endometrial carcinomas." (PMID 34399777, 2021). "Based on the results of this study, 8% of endometrial carcinomas expressed GATA3, which included 2 serous carcinomas, one carcinosarcoma, and one atypical hyperplasia." (PMID 39118796, 2024). "The patient with stage IVB dedifferentiated endometrial cancer (P7) exhibited marked preoperative expression of PanCK and GATA3." (PMID 36768623, 2023). "Exploration of different GATA3 antibodies in uterine MLAs as well as other histological subtypes of endometrial carcinoma would be valuable." (PMID 34829389, 2021). "However, GATA-3 has also been identified as a marker of an aggressive phenotype and poor prognosis in endometrial cancer." (PMID 19707195, 2009). "In addition, weak reactivity of GATA3 has been observed in 7% of endometrial carcinomas." (PMID 28841919, 2017). "Several markers of survival among endometrial cancer (EC) patients have beenproposed, namely, the oncoprotein stathmin, RAF kinase inhibitor (RKIP),Cyclin A, GATA-binding protein 3 (GATA3), and growth and differentiationfactor-15 (GDF-15)." (PMID 35533253, 2022). "Primary colon cancer is usually cytokeratin-7 negative and cytokeratin-20 positive, whereas endometrial cancers are usually cytokeratin-7 positive and cytokeratin-20 negative, and urothelial cancers are often positive for GATA-3." (PMID 40678160, 2025). "Although PAX2 and GATA3 may also stain positive in a small subset of endometrial carcinomas, including EC, they are mostly negative and were only focally and weakly positive in adenocarcinomas of Mullerian origin." (PMID 34441384, 2021).
bladder tumors (14 papers, 2016 to 2025). "We next investigated by real-time PCR expression of the Th2-associated gene GATA-3 in bladder tumors." (PMID 27237631, 2016). "Using surrogate IHC markers, bladder tumours can be classified as luminal when they express GATA3, and CK20, and basal when they show expression of CK5/6 and CK14." (PMID 39856762, 2025). "Intensive yellow staining provided evidence for a prominent co-expression of tumor marker GATA-3 and the AE1/AE3 reactive cytokeratins on UCO#33 by immunofluorescence as well as co-expression of bladder tumor-associated antigens CD24 and of CD44." (PMID 37626918, 2023). "Tumor-associated microenvironment determined High PD-L1 status of GATA3-positive and KRT5/6-expressing bladder tumors detected as the first relapse after TUR without frontline intravesical instillations." (PMID 32455829, 2020). "It is also known that GATA-3 regulates the specification and differentiation of many cell and tissue types, including: innate lymphoid cells (ILC), adipose tissue, endothelial cells, urothelium (a constituent of the bladder tumor environment)." (PMID 27237631, 2016). "However, in our pathology report from the bladder tumor, GATA-3 was negative, consistent with endometrial origin." (PMID 40678160, 2025). "Immunohistochemical staining was positive for GATA-3, 34βE12, CK7 and negative for p63, which were consistent with those observed in bladder tumors." (PMID 40917856, 2025).
Autoimmunity (13 papers, 2014 to 2024). The occurrence of an immune reaction against the organism's own cells or tissues. "Since autoimmunity alters the capabilities of T cells, and T1D is one of these diseases, then GATA3 is proposed to be involved in the underlying pathogenesis of T1D as it is examined in a recent study." (PMID 39768217, 2024). "Our study supports GATA3 function as a potential contributing factor for autoimmunity in JIA and provides a monogenetic mutation that can be used as a tool to better understand this process." (PMID 31238969, 2019). "We are also able to confirm a nominal association of GATA3 variants with another autoimmune condition, namely AAD, in UK, Norwegian and Polish Europeans." (PMID 24614117, 2014). "A total five genes (Fes, Aif1, Gata3, Tlr6, Tlr2) were identified as hub genes that are most likely related to the silicone-induced immune response, four of which (Aif1, Gata3, Tlr6, Tlr2) have been associated with autoimmunity as target genes or disease markers." (PMID 29245939, 2017). "Thus, higher levels of effector memory Tregs expressing GATA3 in high-risk individuals might be explained by cell activation as result of the ongoing autoimmunity preceding disease onset." (PMID 31130961, 2019). "Since the regulatory T cells (Tregs) that are governed by the Foxp3 gene play a protective role against autoimmunity, a connection between GATA3 and the regulation of Treg activity is likely mediated through GATA3’s modulation of Foxp3 expression." (PMID 39768217, 2024). "A total five genes (Fes, Aif1, Gata3, Tlr6, Tlr2) and nine pathways were identified as central participants in the silicone-induced immune response, most of which are also related to autoimmunity." (PMID 29245939, 2017). "Strikingly, most of these hub genes (Tlr2, Tlr6, Aif1, Gata3) have also been reported to be crucial in autoimmunity development." (PMID 29245939, 2017). "Therefore, abnormally high GATA3 expression is responsible for Th2-biased autoimmunity in PV." (PMID 29541411, 2018). "The nominal association of GATA3 alleles with AAD in UK, Norwegian and Polish cohorts, that remained associated following meta-analysis, was a novel finding, as at the time of this study, polymorphisms in the GATA3 gene have not previously been associated with autoimmune conditions." (PMID 24614117, 2014).